OLR1 (oxidized low density lipoprotein receptor 1)
Diseases named in the same sentence as OLR1 in open-access papers (continued):
Sharing a sentence is not in itself a finding about the gene and the disease.
endothelial dysfunction (122 papers, 2009 to 2025). In vascular diseases, endothelial dysfunction is a systemic pathological state of the endothelium (the inner lining of blood vessels) and can be broadly defined as an imbalance between vasodilating and vasoconstricting substances produced by (or acting on) the endothelium. "Soluble lectin-like oxidized low-density lipoprotein receptor-1 (sLOX-1) has emerged as a promising biomarker linked to oxidative stress and endothelial dysfunction, both critical mechanisms in atherogenesis and cardiovascular events." (PMID 40002857, 2025). "Carbamylated proteins can also induce endothelial dysfunction through ROS overproduction and activation of lectin-like oxidized low-density lipoprotein receptor-1 (LOX-1) by uncoupling endothelial nitric oxide synthase (eNOS)." (PMID 40241896, 2025). "This promotes ROS generation, the upregulation of lectin-like oxidized low-density lipoprotein receptor-1 (LOX-1), and endothelial dysfunction, thereby accelerating the progression of MetS and its associated complications." (PMID 40137149, 2025). "As a scavenger receptor, the lectin-like oxidized low-density lipoprotein receptor-1 (LOX-1) can promote endothelial dysfunction and contribute to the development of atherosclerotic cardiovascular disease." (PMID 38037042, 2023). "These lipoproteins bind to endothelial cells by a specific receptor named lectin-like oxidized low-density lipoprotein receptor-1 (LOX-1), and are able to promote endothelial dysfunction since endothelial cells lose their anti athero-trombotic features." (PMID 36768804, 2023). "OLR1 promotes endothelial dysfunction by inducing pro–atherogenic signaling via the endothelial uptake of oxidized LDL (oxLDL), which contributes to the initiation, progression, and destabilization of atheromatous plaques." (PMID 35795669, 2022). "It has been reported that oxHDL binds lectin-like oxidized low-density lipoprotein receptor 1 (LOX-1), promoting endothelial dysfunction through the activation of nuclear factor-κB (NF-κB)." (PMID 36552677, 2022). "Ox-LDL injures endothelial cells directly and contributes to endothelial dysfunction via overexpression of lectin-like oxidized low-density lipoprotein receptor-1 (LOX-1), which induces a further rise in intracellular ROS." (PMID 32566106, 2020). "Furthermore, the adhesion molecules such as intercellular adhesion molecule-1 (ICAM-1) and lectin-like oxidized low-density lipoprotein receptor-1 (LOX-1) play important roles in endothelial dysfunction and vascular injury." (PMID 26881260, 2016). "Lectin-like oxidized low-density lipoprotein receptor-1 (LOX1) is the main ox-LDL receptor of endothelial cells, and ox-LDL, through LOX1, contributes to the induction of endothelial dysfunction, including endothelial apoptosis." (PMID 25801675, 2015). "Not surprisingly, it has been shown that DHA reduces TNF-α-induced endothelial cell injury by inhibiting gene expression related to endothelial dysfunction, such as plasminogen activator inhibitor 1 (SERPINE1/PAI-1) and lectin-like oxidized low-density lipoprotein receptor-1 (LOX1)." (PMID 32878052, 2020).
diabetes (49 papers, 2010 to 2025). "These are likely to stimulate higher expression of OLR1 (oxidized low-density lipoprotein receptor-1) a scavenger of oxidized lipids, often up-regulated in diabetes, with an important role in pregnancy disorders and tumorigenesis." (PMID 29257069, 2017). "OLR1 (OMIM#602601) is a metabolic gene that encodes for the Lectin-like oxidized low-density lipoprotein receptor-1 (LOX-1), a chameleon major receptor with a key role in the development of hypertension, diabetes mellitus, hyperlipidemia, obesity and its complications." (PMID 34439368, 2021).
Hypertension (37 papers, 2009 to 2025). The presence of chronic increased pressure in the systemic arterial system. "As for OLR1 gene, a variation at rs11053646 has been shown to increase the risk of hypertension, myocardial infarction, carotid atherosclerosis, and ischemic stroke." (PMID 37607939, 2023). "Apart from Mmp11 which is a matrix metalloproteinases as Mmp2 we selected Ptgs1, Ptgs2 and Olr1 due to their possible relation to the vascular changes associated with hypertension." (PMID 28880918, 2017). "Olr1 is induced by AngII and is associated with phenotypic changes in VSMCs and hypertension." (PMID 34685676, 2021). "Polymorphism of the Olr1 gene has also been associated with the risk of developing left ventricular hypertrophy in patients with essential hypertension, and hypertrophic remodeling of the vascular wall is a characteristic for hypertension." (PMID 28880918, 2017). "Olr1 was also found to be related to the vascular changes associated with hypertension." (PMID 28880918, 2017). "The increased Olr1 expression in hypertensive cerebral arteries might indicate vascular remodeling and inflammation which also suggest a link between hypertension and the risk of developing secondary complications such as stroke." (PMID 28880918, 2017). "Since Olr1 is an important scavenger receptor with a functional role in hypertension and stroke, the protein level was examined." (PMID 28880918, 2017). "The basal expression of Olr1 in the vascular wall is usually very low, but it can be induced by pro-inflammatory and mechanical stimuli such as hypertension." (PMID 28880918, 2017).
dyslipidemia (34 papers, 2011 to 2025). "OLR1 is primarily expressed in vascularcells and vasculature-rich organs, and its activation by a wide range of stimuli indicativeof dyslipidemia, inflammation and damage initiates several signaling cascadesincluding MAPKs, other protein kinases as well as transcription factors NF-κBand AP-1." (PMID 21637860, 2011). "The focus of the present study was to further elucidate role of OLR1as an oncogene based on the premise that as a sensor of dyslipidemia and a moleculeinvolved in NF-kB activation, OLR1 may be a link betweendyslipidemia and cancer." (PMID 21637860, 2011). "OLR1 (oxidized low-density lipoprotein (LDL) receptor 1) was a possible link between obesity, dyslipidemia, and cancer." (PMID 35651784, 2022).
myocardial infarction (34 papers, 2008 to 2025). Gross necrosis of the myocardium, as a result of interruption of the blood supply to the area, as in coronary thrombosis. "For instance, specific polymorphisms linked to the OLR-1 gene have been correlated with higher susceptibility to coronary artery disease and myocardial infarction." (PMID 38791315, 2024). "The lectin-like oxidized LDL receptor LOX-1 (encoded by OLR1) is believed to play a key role in atherogenesis and some reports suggest an association of OLR1 polymorphisms with myocardial infarction (MI)." (PMID 18384690, 2008). "Moreover, OLR1 polymorphisms were associated with increased susceptibility to acute myocardial infarction (AMI) and coronary artery diseases (CAD)." (PMID 26542080, 2016). "The association of polymorphisms in the human OLR1 gene with the susceptibility to myocardial infarction (MI) has been reported." (PMID 23935243, 2013). "Moreover, a study of a group of 150 patients with acute myocardial infarction (MI) vs. a control group of 103 healthy individuals identified SNPs in OLR1 associated with increased risk of MI." (PMID 33182772, 2020).
Obesity (31 papers, 2011 to 2025). Accumulation of substantial excess body fat. "Recent studies have demonstrated that OLR1 is closely linked to obesity, and it was found to be highly expressed in fat pigs compared to lean animals." (PMID 29739312, 2018). "OLR1 (oxidized low‐density lipoprotein receptor 1) can bind and degrade oxidized low‐density lipoproteins, and is expressed in a variety of cell types and closely linked to obesity." (PMID 35592278, 2022). "We believethese data strongly suggest that OLR1 may function as a linkbetween obesity and susceptibility to breast cancer." (PMID 21637860, 2011). "Recently, OLR1 has indicated as link between obesity and cancer." (PMID 26061746, 2015). "Thus, the effects of OLR1 in obesity could be related to a complex state of inflammation and adipocyte death." (PMID 24040759, 2013). "One of these mechanisms involves oxidized low density lipoprotein receptor 1 (OLR1), as a link between obesity and cancer." (PMID 26061746, 2015).
Stroke (30 papers, 2014 to 2025). Sudden impairment of blood flow to a part of the brain due to occlusion or rupture of an artery to the brain. "Allelic polymorphisms within the human OLR1 locus that encodes LOX-1 are associated with altered risk of cardiovascular disease and stroke." (PMID 37805141, 2023). "This is supported by clinical data, since Olr1 was found in early atherosclerotic plaque from ischemic patients and correlated to the risk of having a stroke using a meta-analysis." (PMID 28880918, 2017). "ED has been linked to plaque rupture and stroke and, as far as Mox-LDL isconcerned, we have previously reported that Mox-LDL activates ED by binding tothe lectin-like oxidized low-density lipoprotein receptor-1 (lox-1) scavengerreceptor." (PMID 39077081, 2023). "Six proteins (AGFG2, C1QTNF1, CHIT1, DNAJC15, FTL, and OLR1) have been reported to be implicated in other neurodegenerative diseases such as AD, ALS, or stroke, but not in PD." (PMID 37422510, 2023). "Soluble lectin-like oxidized low-density lipoprotein receptor-1 (sLOX-1) may be a potential biomarker of coronary artery disease (CAD) and stroke." (PMID 31772687, 2019).
breast carcinoma (29 papers, 2011 to 2025). "Therefore, OLR1 may function in special situations, such as obesity and chronic inflammation, to increase breast cancer susceptibility." (PMID 31208017, 2019). "Collectively, these findings delineated a significant promotional effect of OLR1 on breast cancer progression, with the darkest color, highest AUC value, and greatest risk, while a notable protective function of PNPLA2." (PMID 40282270, 2025). "For example, GLRX, SNAP23 and OLR1 are overexpressed, which is related to aggressive metastasis in breast cancer and prostate cancer tissues." (PMID 38017548, 2023). "OLR1 activated by NF-κB plays an enhancing role in adhesion and migration in monocytic and breast cancer cells." (PMID 37047804, 2023). "siRNA-mediated inhibition of OLR1 expression suppresses the growth of breast cancer cells and reduces the tumorigenicity, highlighting its importance for the maintenance of transformed state." (PMID 33402733, 2021). "For example, TBC1D3 is observed to be overexpressed in breast cancer by promoting oxidized low-density lipoprotein receptor 1 expression required for cell migration involving in TNFα/NF-κB signaling." (PMID 33194704, 2020). "Previous studies indicated that upregulation of OLR1 would promotes migration of breast cancer cells, which was the same as our current findings." (PMID 31718700, 2019). "The human breast cancer cell line HCC1143 showed increased OLR1 expression compared with the normal mammary epithelial cell line MCF10A." (PMID 31208017, 2019). "The second partdefines the relationship between olr1 and apoptosis and lipogenesisgenes in breast cancer cell line HCC1143 and migration and adhesion of thesecells." (PMID 21637860, 2011). "Additionally, previous research has confirmed the roles of these five central genes (CEACAM6, CAMP, PNPLA2, OLR1, and ADIPOR1) in breast cancer, which were consistent with our predictions of risk and protective factors." (PMID 40282270, 2025). "Upregulated genes like INHBA, PSMD2 and OLR1 play a crucial role in breast cancer (BC) which may bring us some similarities between HNSCC and BC." (PMID 39749326, 2024). "OLR1 overexpression revealed a poor prognosis in breast cancer and might represent a potential therapeutic target for breast cancer patients." (PMID 38291367, 2024). "Furthermore, it was also demonstrated the contribution of the oncogene TBC1D3 in the migration of human breast cancer cells upregulating OLR1, through the control of TNFα/NF-κB signaling." (PMID 33402733, 2021). "Moreover, the overexpression of OLR1 has been detected in breast cancer tissues, and enhanced OLR1 expression is able to increase breast cancer cell proliferation." (PMID 34921134, 2021). "Moreover, upregulation of OLR1 in breast cancer cell lines enhanced cell migration." (PMID 31208017, 2019). "The results demonstrated that the expression levels of OLR1, ADIPOR1, CEACAM6, DNASE2, CD53, BMF, and CAMP were significantly elevated in breast cancer samples compared to healthy controls (p < 0.05)." (PMID 40282270, 2025). "OLR1, GLRX and SNAP23 were overexpressed in human prostate and breast cancer tissues and high expression levels of these molecules are associated with aggressive phenotype and metastatic stage." (PMID 23292678, 2013). "Furthermore, OLR1 is overexpressed in a coordinated way with other lipid metabolic genes (GLRX and SNAP23) in late-stage breast cancer tissues." (PMID 33402733, 2021).
coronary artery disease (29 papers, 2014 to 2025). "OLR1 (Oxidized low-density lipoprotein receptor-1) is increased in atheromatous plaques, while serum levels of ORL1 are raised in coronary artery disease patients." (PMID 28323859, 2017).
acute coronary syndrome (27 papers, 2014 to 2025). Signs and symptoms related to acute ischemia of the myocardium secondary to coronary artery disease. "Soluble lectin-like oxidized low-density lipoprotein receptor-1 (sLOX-1), neutrophil gelatinase-associated lipocalin (NGAL), and matrix metalloproteinase-9 (MMP-9) are inflammatory biomarkers involved in plaque destabilization resulting in acute coronary syndrome (ACS)." (PMID 33214686, 2020).
hyperlipidemia (20 papers, 2014 to 2025). "Oxidized low-density lipoprotein (ox-LDL) and lectin-like oxidized low-density lipoprotein receptor 1 (LOX-1) in human degenerative EPC is associated with hyperlipidemia (HLP)." (PMID 41294811, 2025). "Our work identified miR-21a-5p as a potential regulator of aerobic exercise affecting lipid metabolism, achieved the favorable goal in hyperlipidemia by synergistically inhibiting the expression of target genes FABP7, HMGCR, ACAT1, and OLR1." (PMID 34099844, 2021). "Taken together, these results demonstrated that aerobic exercise improved hyperlipidemia through miR-21a-5p-induced inhibition of target genes FABP7, HMGCR, ACAT1, and OLR1." (PMID 34099844, 2021). "And we think one of the mechanisms by which aerobic exercise improved hyperlipidemia was to up-regulate the expression of miR-21a-5p, thus inhibited the expression of target genes FABP7, HMGCR, ACAT1, and OLR1, which were closely related to lipid metabolism." (PMID 34099844, 2021). "miR-21a-5p improved hyperlipidemia via the inhibition of its targets FABP7, 3-hydroxy-3-methylglutaryl CoA reductase (HMGCR), acetyl CoA acetyltransferase 1 (ACAT1), and oxidized low-density lipoprotein receptor 1 (OLR1)." (PMID 39872853, 2023).
colon carcinoma (19 papers, 2014 to 2025). "Increased expression of OLR1 in pancreatic and colon cancer has been associated with metastasis and poor prognosis." (PMID 35323693, 2022). "Research revealed that silencing OLR1 attenuates glycolytic metabolism, thereby inhibiting proliferation and chemoresistance in colon cancer cells." (PMID 39494300, 2024). "SULT2B1 expression was diminished by downregulating c-MYC, thereby restraining glycolytic metabolism to inhibit colon cancer cell proliferation and chemoresistance under condition of knockdown of OLR1." (PMID 37337170, 2023). "Colon cancer tissues and LoVo cells were attained, where OLR1, c-MYC, and SULT2B1 expression was detected by immunohistochemistry, RT-qPCR, and western blot analysis." (PMID 34921134, 2021). "The results displayed that the survival rate of colon cancer patients with high expression of OLR1 was strikingly decreased." (PMID 34921134, 2021). "Based on the results of Kaplan-Meier, the overall survival of colon cancer patients with OLR1 low expression was dramatically longer than that in patients with high expression, which was consistent with the biological prediction." (PMID 34921134, 2021). "In order to further verify that OLR1 regulated the proliferation and chemoresistance of colon cancer cells by promoting c-MYC, OLR1 was knocked down and/or c-MYC was overexpressed in colon cancer cells." (PMID 34921134, 2021). "The MTS assay, clone formation assay, and Ki67 expression also manifested that overexpression of SULT2B1 annulled the suppression of the proliferation of colon cancer cells triggered by OLR1 knockdown." (PMID 34921134, 2021). "A similar trend observed in the data of a prior research that OLR1 upregulation accelerated colon cancer onset, progression, and metastasis." (PMID 34921134, 2021). "As detected by MTS assay, colony formation assay, and RT-qPCR, the proliferation, colony formation, and Ki67 expression of LoVo colon cancer cells was apparently decreased by sh-OLR1 treatment, which was abrogated by further oe-c-MYC treatment." (PMID 34921134, 2021). "The cells treated with sh-NC or sh-OLR1 were injected subcutaneously into nude mice to establish nude mice model of colon cancer." (PMID 34921134, 2021). "The OLR1 stably knockdown cell lines and control cell lines were constructed to explore the regulation of c-MYC expression by OLR1 in colon cancer cells and its effect on the function of colon cancer cells." (PMID 34921134, 2021). "Meanwhile, MTS test and clone formation test exhibited knockdown of OLR1 remarkably decreased the proliferation and clone formation of colon cancer cells." (PMID 34921134, 2021). "In order to further determine the role of OLR1 in colon cancer, the clinical data (COADREAD) of colon cancer in the TCGA were analyzed by GEPIA." (PMID 34921134, 2021). "From RT-qPCR result, OLR1 and c-MYC mRNA expression was obviously diminished in OLR1-silenced colon cancer cells, while in the presence of sh-OLR1, elevated c-MYC mRNA expression was observed in colon cancer cells after further oe-c-MYC treatment." (PMID 34921134, 2021). "A similar finding was noted in our work that OLR1 knockdown diminished c-MYC expression to suppress colon cancer cell glycolytic metabolism, proliferation, and chemoresistance." (PMID 34921134, 2021). "In brief, OLR1 was highly expressed in colon cancer tissues, and was negatively correlated with survival time of colon cancer patients, and positively correlated with lymph node metastasis and tumor infiltration depth of colon cancer patients." (PMID 34921134, 2021). "Collectively, the expression pattern, prognostic effect, immune-inhibitory activity demonstrated the oncogenic effect of COL5A2, EDNRA, and OLR1 in colon cancer." (PMID 31500382, 2019). "Mechanistically, OLR1 increased c-MYC expression to upregulate SULT2B1 in colon cancer cells." (PMID 34921134, 2021).